ARG1 (arginase 1)
Diseases named in the same sentence as ARG1 in open-access papers (continued):
Sharing a sentence is not in itself a finding about the gene and the disease.
tumor (continued). "In 47 patients (55.95% of the samples) a moderate ARG1 expression was observed with ARG scores of 100–180 and 28 (33.33%) of the tumors showed weak ARG1 expression (ARG scores below 100) with up to 50% of tumor cells stained weakly, and rest of the cells scored as negative." (PMID 31278254, 2019). "Consequently, the ratios of CTLs to Tregs and to Arg1+ MDSC were significantly enhanced with the triple combination therapy of ML-RR-CDA administration into the flank tumor combined with systemic α-PD-1 and α-CTLA-4." (PMID 31533840, 2019). "Moreover, the upregulation of CAT2 is coordinated with the induction of both NOS2 and ARG1, thus further favoring Arg uptake by MDSCs at the tumor site." (PMID 31354721, 2019). "As such, the tumor cells may adapt to a low-arginine condition and be unaffected by PEGylated ARG1 treatment." (PMID 30808864, 2019). "High-endogenous ARG2 in tumor cells may lower the intratumoral arginine level similar to ARG1 treatment with cells adapting to a low intratumoral arginine environment." (PMID 30808864, 2019). "Furthermore, in ID8-ARG1 bearing-mice up to 1% of peritoneal activated CD11c+ dendritic cells stained positive for V5-tag indicating an uptake of tumor-derived ARG1." (PMID 31278254, 2019). "The overriding objective was to determine whether OvCa-derived EVs may contain ARG1 and suppress anti-tumor functions of T-cells thus providing the tumor with an advantage to escape from the host immune system." (PMID 31278254, 2019). "To determine whether cytokine and eHsp70 profile modulation in the TME is associated with the pro-tumor conversion of monocytic THP1 cells, we examined the expression of the F4/80 and arginase-1 markers using western blotting and flow cytometry." (PMID 31861801, 2019). "Consistent with the results obtained in vivo with the EVs-ARG1 in the adoptive transfer model in non-tumor settings, ID8-ARG1 bearing-mice had a significantly reduced percentage of activated CD69-positive CD4+ and CD8+ T-cells in the peritoneal cavity relative to mice bearing control tumor cells." (PMID 31278254, 2019). "In cancer, MDSCs (CD34+CD33+CD13+CD15(−)) promote tumor cell growth and suppresses immune cell function through production of arginase 1 (ARG1) which synergizes with inducible nitric oxide synthase (iNOS) to increase superoxide and nitric oxide (NO) production, thus, reducing lymphocyte function." (PMID 31430935, 2019). "Exosome liberated miR-310a-30p is understood to polarize macrophages into an M2 phenotype via the activation of PTEN/P13Kγ signalling, favouring the malignant properties of tumour cells, due in part to the expression of the anti-inflammatory cytokine (IL-10) and arginase-1 (Arg1)." (PMID 31835751, 2019). "Serum ARG1 levels in ID8-ARG1 tumor-bearing mice increased concomitantly with the tumor growth." (PMID 31278254, 2019). "So, the high level of Arg-1 in macrophage could be helpful for anti-tumour immunity after cryo-thermal therapy." (PMID 31519961, 2019). "TEXs could significantly induce the accumulation of MDSCs expressing cyclo-oxygen-ase 2 (Cox2), IL-6, VEGF, and Arg1, and promote the tumor progression." (PMID 31438991, 2019). "We propose that high-endogenous expression of ARG2 could impede the anti-tumor effect of PEGylated ARG1 in lung SCC." (PMID 30808864, 2019). "ARG1 was also expressed in tumor cells isolated from the ascites of an OvCa patient." (PMID 31278254, 2019). "However, they also found that GM-CSF secreted from the tumor cells resulted in higher expression of immunosuppressive genes, such as arginase 1 (ARG1), within the myeloid population." (PMID 31396227, 2019). "In mice that are subcutaneously injected with CT26 colon cancer cells, single treatment with a small molecule ARG1 inhibitor (CB-1158) or an anti-PD-L1 antibody suppresses the tumor growth, and their tumor suppressive effect is enhanced by combining these two inhibitors." (PMID 29670880, 2018).
tumor (continued). "The present study found that YHD could decrease the number of MDSCs and downregulate the expression of iNOS and ARG-1 in the tumor microenvironment." (PMID 30581487, 2018). "Similarly, NO-releasing aspirin was shown to reduce ARG-1 and iNOS, and enhance the number and function of tumor-specific T cells." (PMID 30233579, 2018). "It has been demonstrated that some miRNAs such as miR-494, miR-155, and miR-21 are fundamental for the recruitment of MDSCs to the tumor site, contributing to the modulation of their immunosuppressive function and to tumor growth by regulating the production of ARG1 and iNOS." (PMID 30443251, 2018). "Thus, we examined gene expression to identify M1/inducible nitric oxide synthase (iNos)- and M2/arginase 1 (Arg1)-expressing macrophages on isolated tumour tissue derived from control, Il6rαKO and Il6rαmyl-KO mice." (PMID 29695802, 2018). "Futhermore, IL-6 deletion did not affect iNOS expression, but remarkedly inhibited arginase-1 expression in tumor-associated F4/80+ macrophages, supporting the important role of endothelial IL-6 in macrophage alternative activation." (PMID 29422647, 2018). "In addition to TAM and T lymphocytes that have a key role in tumor progression, the myeloid cell population can suppress T-lymphocyte activity by the expression of arginase 1 (ARG1) and nitric oxide synthase 2 (NOS2)." (PMID 30545144, 2018). "To further dissect the relationship between activated Wnt/β-catenin signaling and M2 macrophages in HCC patients, we determined the expression of CD68 (a pan macrophage marker), β-catenin and M2-related markers MR or Arg1 in 25 frozen tumor sections by immunofluorescence staining." (PMID 30022048, 2018). "Finally, CD11b+ cells of spleen and local lymph nodes showed increased expression of the M2 tumor supporting macrophage marker arginase 1 (Arg1) in Shb knockout mice." (PMID 29721156, 2018). "Interestingly, Gr-1+CD11b+ cells from treated 4T1 tumor-bearing mice showed a decreased expression of ARG1, TGFβ1, and IL-10, factors that are critical in mediating immune suppression in Gr-1+CD11b+ cells." (PMID 29973593, 2018). "In MC-38 tumor models, we demonstrated that TgMGLL stimulated the expression of proinflammatory cytokines (IL-1β and TNFα) and reduced the levels of anti-inflammatory cytokines (IL-10, Arg-1, and TGFβ) in a CB2-dependent manner in TAMs." (PMID 29968710, 2018). "A surprising observation from our microscopy-based analysis of TAMs in a spontaneous murine breast tumor model, was that Arg1-expressing TAMs were almost exclusively located within ischemic tumor regions, while Mrc1-expressing TAMs were found in perivascular and other well-nurtured tumor regions." (PMID 29991530, 2018). "A study conducted by Corzo and colleagues showed that tumor-infiltrating MDSCs suppressed both antigen-specific and non-specific T-cell activity, which was accompanied by up-regulation of Arg1 and iNOS, and down-regulation of NADPH oxidase and reactive oxygen species (ROS)." (PMID 30619850, 2018). "Similarly, arginase-1 plays an indirect role in angiogenesis through reorganization of the tumor ECM and contributes for the generation of essential metabolites during cell division, such as polyamines, supporting cancer cells growth." (PMID 29629338, 2018). "The production of Arg1 by MDSCs from tumor tissue was significantly downregulated (P < 0.01)." (PMID 29914443, 2018). "Whether ARG2 is involved in the effect of ARG1 on tumor growth still requires further exploration in the future." (PMID 30320132, 2018). "Several other molecules in the tumor endothelium, such as programmed cell death-1 ligand (PD-L1), B7-H3, arginase-1 (ARG-1), indoleamine 2,3, dioxygenase (IDO), IL-10, and PGE2, released by endothelial cells, downregulate TIL function or kill CD8+ effector TILs." (PMID 30200478, 2018).
tumor (continued). "Many of the molecules that inhibit T-cell responses such as ARG1 and ROS are present in both activated neutrophils and G-MDSCs, and at least ROS has also been shown to have a direct anti-tumor function by inducing tumor cell lysis." (PMID 27690299, 2017). "Likewise, nitric oxide-releasing aspirin (a typical aspirin linked to a nitric oxide donor) reduces arginase 1, NOS2, and PNT, while increasing the frequency and function of tumor-specific T cells, thus boosting the antitumor effect of cancer vaccination." (PMID 28223985, 2017). "Interestingly, we also noted two distinct patterns of Arg1 expression, either strong staining observed in the stromal capsule surrounding the tumor or clustered staining distributed within the tumor." (PMID 28807001, 2017). "The lactate-induced expression of Arginase-1 was shown to induce tumor growth." (PMID 28471401, 2017). "Arg1 and iNOS were also expressed to some extent by other cells in the tumor microenvironment." (PMID 29164051, 2017). "In addition to tumor expression, Arg1 protein and activity have been observed in the peripheral blood and have been reported to be higher in the plasma of some cancer patients compared to healthy volunteers." (PMID 29254508, 2017). "To investigate which tumor types may be more likely to respond to arginase inhibition, we interrogated human tumor microarrays by immunohistochemistry for Arg1 protein expression." (PMID 29254508, 2017). "Arg-1 and iNOS are both highly expressed in MDSCs derived from tumor bearing mice." (PMID 28002798, 2017). "However, selumetinib treatment reduced baseline tumor expression of Arg1, and reverses the increased Arg1 expression induced in tumor cells by CTLA-4 blockade." (PMID 28807001, 2017). "Most of the bacteria (for instance B. xylanisolvens, Paraprevotella clara, Prevotella timonensis) were positively relating with anti-inflammatory/tumor markers (e.g. Trem-2, MR, arginase-1, TNF-α) and negatively correlating with pro-inflammatory/tumor markers (e.g. IL-12, IL-6 and iNOS)." (PMID 28970547, 2017). "Of note, the significant tumor growth inhibition in mice treated with the combination of CB-1158 plus T cells is consistent with the striking survival benefit that was reported for T cell therapy in mice deleted for myeloid Arg1." (PMID 29254508, 2017). "However, in contrast to MP and Gr1+ cells that expressed Arg1 shortly after tumor trafficking, Arg1 expression in MG was delayed and occurred in larger tumors." (PMID 27936099, 2016). "Most of the Arg1+ cells in this model were in the tumor mass itself." (PMID 27936099, 2016). "In addition to lactic acid production and glucose metabolism, MDSCs, M2-like MΦs and cancer cells, also affect the tumor microenvironment through degradation of extracellular arginine levels via arginase 1 (Arg1) expression." (PMID 26885366, 2016). "As vaccination with AdC68-mFAP given together with AdC68-gDMelapoly reduced iNOS and Arg1 expression in MDSCs and TAMs of tumor-bearing mice, we analyzed whether the functional reductions of ISCs were linked to changes in STAT activation." (PMID 26943036, 2016). "This could likely be due to the infiltration of Arg1+ M2-type macrophages to the sight of inflammation surrounding/within the tumor with the purpose of cleaning the inflamed site or to initiate resolution of the inflammation." (PMID 27851813, 2016). "To investigate functional impact of cryo-thermal therapy on MDSCs, we isolated MDSCs from spleen of treated mice and tumor-bearing control group, and the mRNA expression of arginase-1(Arg-1) and inducible nitric synthase (iNOS) in MDSCs was quantified by RT-PCR." (PMID 27256519, 2016). "However, to assess changes in TAM Arg1 expression with tumor growth, Arg1 expression was also analyzed in myeloid cells at different stages of tumor progression." (PMID 27936099, 2016).
tumor (continued). "To determine whether SHIP regulated M1/M2 polarization in the 67NR tumor model, we isolated pulmonary CD11b+Gr1+ cells and peritoneal Mφs to assess Arg1 expression." (PMID 26683227, 2016). "Besides PDE-5 inhibitors, the activity of iNOS and ARG-1 was found to be blocked by corresponding inhibitors or by nitroaspirin leading to the stimulation of T cell functions and anti-tumor effects." (PMID 27827871, 2016). "The MDSCs can inhibit T cell-mediated tumor acquired immune responses with overexpression of Arg1, iNOS, and Ros, suppress NK cell cytotoxicity by inhibiting NKG2D and IFN-c, and facilitate angiogenesis by releasing vascular endothelial growth factor (VEGF), MMPs, and TGF-β." (PMID 27042656, 2016). "As Arg1 is significantly expressed in the liver in general and as our previous results indicate the significance of Arg1 in tumor metastasis to lung tissue of the model, we next determined if there was an effect of PLD inhibitors on liver Arg1 in samples from our model." (PMID 27851813, 2016). "Hence, it is possible that ILC2s inhibit T cell responses in the tumor microenvironment via their Arg1 activity and upregulation of Arg1 in myeloid cells." (PMID 28536374, 2016). "Although many of MPs expressed Arg1, other tumor-infiltrating cells were also Arg1+." (PMID 27936099, 2016). "This ~10 fold increase in Arg1+ cells in the absence of a significant increase in CD11b+ cells suggests that IL-4 produced by tumor cells promoted M2 polarization of tumor associated myeloid cells in vivo." (PMID 27563494, 2015). "Interestingly, arg-1 expression was high in tumor and in vitro-generated MDSC (both monocytic and granulocytic subsets) but not in splenic MDSC." (PMID 25869209, 2015). "Arg-1 was highly expressed in the simulated tumor microenvironment group." (PMID 26462177, 2015). "However, the frequency of Arg1 staining cells was elevated ~10 fold in the IL4-AC2M2 cohort, suggesting that IL-4 was influencing the polarization of these tumor associated myeloid cells (P=0.0012)." (PMID 27563494, 2015). "One mechanism by which MDSCs may promote tumor growth is through expression of arginase-1, which in turn diminishes T cell mediated anti–tumor responses." (PMID 25528766, 2015). "Alterations in arginase-1 activity in the tumor microenviroment also provide a possible explanation for concomitant tumor immunity induced by MCA-205-OVA tumors in the presence of a progressive primary MCA-205-OVA tumor." (PMID 24614600, 2014). "This shows that both inhibitors predominantly inhibit the macrophage Arg1 pathway, but may also act directly on the tumor cells." (PMID 25294815, 2014). "We assessed the expression of iNOS and Arg-1 on the MDSCs from the BM of tumor-bearing mice." (PMID 24605110, 2014). "The mechanism whereby tumor cells that express E1A lead to the decreased expression of arginase-1 by TAMs is unknown and also needs to be explored." (PMID 24614600, 2014). "Both Arginase-1 and iNOS are highly expressed in MDSCs of tumor bearing mice." (PMID 24981055, 2014). "Determining how E1A is able to inhibit tumor cells from inducing arginase-1 in TAMs could have important implications in augmenting local anti-tumor immune responses in the setting of progressive tumor enlargement." (PMID 24614600, 2014). "Similarly, phosphodiesterase-5 inhibitors delay tumor progression by decreasing Arg1 and iNOS expression and by regulating the suppressive machinery of MDSCs." (PMID 24995313, 2014). "Besides the suppression of the anti-tumor activity of T and NK cells by means of arginase 1 and inducible nitric oxide synthase (iNoS), MDSCs can foster tumor growth by releasing MMPs that increase the bioavailability of VEGF within the tumor microenvironment." (PMID 24782982, 2014). "The expression of Arg1 and Nos2 by tumor infiltrating immune cells was therefore evaluated by qPCR." (PMID 24982761, 2014).
tumor (continued). "ARG1 mediated depletion of L-arginine from the tumor microenvironment may be one of the mechanisms of MDSC induced T cell suppression secondary to decreased expression of the ζ subunit of CD3." (PMID 24829747, 2013). "Regamonti and colleagues were able to demonstrate that treatment of C57BL/6 mice implanted with TRAMP-C1 prostate cancer cells with L-NAME resulted in reduction in the immunosuppressive action of CD11b+ myeloid cells (including inhibition of Arg1 activity) in the spleen and within the tumor." (PMID 24829747, 2013). "Furthermore, PGE2 produced by the tumor induces arginase 1 and cationic amino acid transporter (CAT)-2B in MDSCs, both of which deplete arginine from the tumor microenvironment and impair T-cell function." (PMID 24202450, 2013). "In a mouse model of lymphoma, MDSCs were shown to induce Treg expansion through a mechanism that involved Arg-1 and the capture, processing, and presentation of tumor-associated antigens by MDSCs but was independent of TGF-β." (PMID 22481970, 2012). "Although ARG1 is used as a typical pro-tumoral marker gene, the simplistic convention of M1/M2 states is mostly applicable to in vitro experiments, whereas TAMs exist in a full spectrum of phenotypes and functions shaped by the nuances of the tumor microenvironment." (PMID 40095115, 2025). "This properdin deficiency results in low levels of IL-1b mRNA and higher levels of arginase-1, monocyte chemotactic protein-1 (MCP-1), and IL-10 mRNAs, suggesting that a properdin-deficient tumor microenvironment may induce a profile of M2 macrophages with pro-tumoral activity." (PMID 40370471, 2025). "Within the TME, ARG-1 plays a crucial role in immune evasion by activating immunosuppressive cells, such as myeloid-derived suppressor cells (MDSCs), a heterogeneous population of bone marrow-derived cells that suppress immune responses and facilitate tumour progression." (PMID 39861764, 2025). "Therefore, targeting the uptake, transport and metabolism of Arg, reversing the expression imbalance of iNOS/ARG1 and reshaping the metabolic pattern of TAMs have become important strategies to intervene in the polarization of TAMs and inhibit their tumor-promoting function." (PMID 41281760, 2025). "In CRC, neutrophils exhibit a dual role: in early-stage tumors or under specific therapies, they may trigger cytotoxic effects against tumor cells, while in advanced stages, they are more likely to employ ROS and arginase-1 to suppress T-cell activity and promote a pro-metastatic niche." (PMID 40387965, 2025). "To investigate whether FIH can regulate myeloid Arg1 expression in response to signals secreted by tumor cells, we treated FIH+/+ and FIHΔ1-2/Δ1-2 BMDMs with media that were conditioned by B16 or LLC cell culture supernatants (tumor cell-conditioned medium, TCM)." (PMID 38422022, 2024). "Moreover, the expression of IDO, ARG-1, and iNOS was decreased in tumor tissues." (PMID 38641823, 2024). "Since FIH deficiency enhances ARG1/Arg1 expression in macrophages and promotes chemotaxis, we investigated whether FIH-deficient macrophages are more likely to infiltrate tumors to form tumor promoting TAMs in vivo." (PMID 38422022, 2024). "Additionally, ginseng-derived PELNs reprogram TAMs and enhance the function of CD8 Teff via the mTOR-T-bet axis to regulate arginase-1 (ARG1) release thereby downregulating immune checkpoint expression on T cells in the tumor microenvironment (TME) and ameliorating T cell exhaustion." (PMID 39239509, 2024). "ARG1 is a cytoplasmic protein, while ARG2 is mainly localized in the mitochondria, closely associated with poor prognosis through degradation of L-arginine and thus inhibiting the anti-tumor effects of various types of cells in TME antitumor effects and promotes tumor cell proliferation." (PMID 39239650, 2024).